SIX1 (SIX homeobox 1)
Diseases named in the same sentence as SIX1 in open-access papers (continued):
Sharing a sentence is not in itself a finding about the gene and the disease.
tumor (continued). "Interestingly, while Six1 overexpressing luminal cells are uniquely dependent on TGF-β signaling to increase TIC populations in vitro, they are no more dependent than control cells on MEK/ERK signaling to induce some TIC characteristics in vitro, and for tumor initiation in vivo." (PMID 22765220, 2012). "SIX1 and NCAM expression is usually not seen in stromal WT elements, but was detected in tumor material WT05, indicating less differentiated, immature stroma in this tumor and corresponding spheroid cultures." (PMID 31562394, 2020).
cancer (96 papers, 2006 to 2025). A tumor composed of atypical neoplastic, often pleomorphic cells that invade other tissues. "SIX1 was found to attenuate cancer stemness, was associated with poor prognosis, and reduced sensitivity to 5-FU in HCC." (PMID 39199296, 2024). "Previously, we reported that MA inhibited casein kinase alpha (CK2α) and its downstream target SIX1 oncoprotein, which is associated with tumorigenesis and invasiveness of multiple cancer types." (PMID 38605607, 2024). "The pro-metastatic functions of SIX1 in carcinomas have been primarily linked to this EMT-promotional role." (PMID 37468459, 2023). "Previous studies have indicated that SIX1, a transcription factor involved in embryonic development, is frequently dysregulated in numerous human cancers, and its increased expression is associated with poor clinical outcomes." (PMID 35069900, 2022). "As an exploratory study, our results have shown that loss of Six1 in cancer cells can induce long-lasting antitumor immune responses." (PMID 34782761, 2021). "Collectively, these data suggested that cellular immune responses, particularly CD8+ T cell responses, were activated in TMEs containing Six1-deficient cancer cells." (PMID 34782761, 2021). "Six1 has been found to transcriptionally regulate genes encoding cyclin A1 and cyclin D1 in developmental and cancer contexts." (PMID 34490256, 2021). "Using CRISPR/Cas9-mediated knockout of the Six1 gene in cancer cells, we studied the impact of Six1 deficiency on the triggering of antitumor immunity in the TME and explored the potential mechanisms both in vitro and in vivo." (PMID 34782761, 2021). "To further understand the molecular mechanisms by which Six1-deficient cancer cells trigger T cell activation in the TME, we performed another RNA-Seq analysis to identify DEGs between WT and Six1−/− MCA205 cells (GSE183580)." (PMID 34782761, 2021). "We constructed 27 studies and estimated the association between SIX1 expression in various cancer patients' overall survival and verified with TCGA datasets." (PMID 34745930, 2021). "We also found that Six1-deficient cancer cells developed into tumors only in immunodeficient mice, not in immunocompetent mice." (PMID 34782761, 2021). "The results showed that while a large amount of collagen VI was deposited outside WT cancer cells, significantly reduced collagen deposition was observed around Six1-deficient cancer cells." (PMID 34782761, 2021). "The association between miR-489-3p and SIX1 was further validated using external datasets from TCGA (The Cancer Genome Atlas)." (PMID 32258386, 2020). "Overexpression of SIX1 is associated with many human cancers, while mutations in the human SIX1 cause Branchio-Oto-Renal (BOR) or Branchio-Oto (BO) syndrome." (PMID 31956913, 2020). "Drosophila So has not been shown to control the expression of cytoskeleton component genes, but the murine So homolog Six1 directly activates Vil2, which encodes the actin cytoskeleton regulator Ezrin, thus promoting cell motility and metastasis in cancer." (PMID 24586968, 2014). "The aberrant expression or mutation of SIX1 has been linked to several disorders, including cancer." (PMID 39199296, 2024). "MiRNAs that function as oncogenes or tumor suppressors may target SIX1 to promote or suppress cancer development and are thus linked to cancer cell metabolism and apoptosis." (PMID 36276846, 2022). "SIX1 expression is associated with increased proliferation of the cancer cells." (PMID 35420997, 2022). "SIX1 is overexpressed in human cancers and is associated with tumorigenesis." (PMID 33686961, 2021). "Intriguingly, SIX1 was tightly linked to EYA1 in malignant tumor." (PMID 31921695, 2019). "Interestingly, SIX1 is also linked to stem and progenitor cell specification both in development and cancer (see Introduction)." (PMID 30723235, 2019).
cancer (continued). "Since Six1 and Eya are typically downregulated in healthy tissues after development is complete, they represent ideal targets for new cancer therapies." (PMID 40414499, 2025). "In another pathway, LRRC75A-AS1 delivered by M2 macrophage exosomes has been shown to promote cancer progression by inhibiting miR-429, which upregulates sine oculis homeobox homolog 1 (SIX1) levels and activates the STAT3/MMP-9 axis." (PMID 41291696, 2025). "As the activator of the Six1–Eya bipartite transcription factor complex, Eya mediates critical functions in cancer by promoting proliferation, angiogenesis, plasticity, immune evasion, invasion, metastasis, and epithelial–mesenchymal transition." (PMID 40414499, 2025). "It has been found that SIX1 signaling is reactivated in various cancers and can regulate cell proliferation and invasion by modulating the cell cycle and epithelial-mesenchymal transition." (PMID 39623295, 2024). "Given its roles in cell growth and developmental pathways, SIX1 is considered a potential target for therapeutic intervention in cancer and developmental disorders." (PMID 39199296, 2024). "Among them, ephrin receptor EPHA4, actin binding LIM-proteins ABLIM1 and ABLIM2, semaphorin SEMA7A and glial neurotrophic factor GFRA2 genes, which are involved in axon guidance, are commonly repressed in cancer cells by DiPRO1 and SIX1." (PMID 39009887, 2024). "SIX1 also marks neonatal DES exposure-induced cancer cells and is found in some human endometrial cancers." (PMID 37856394, 2023). "SIX1 is also involved in the regulatory axis of Circular RNA and microRNAs to promote cancer proliferation, migration and invasion." (PMID 37723477, 2023). "In cancer, SIX1 overexpression induces EMT in a wide range of cancer cell types, including those derived from breast tissue." (PMID 38031089, 2023). "The present study further explored the expression of SIX1 in the expO dataset according to the patient stage in 3 types of cancer (liver, colon, and breast); interestingly, the expression levels of SIX1 were upregulated according to the patient stage." (PMID 37427884, 2023). "The study showed that SIX1 strengthened the special subgroup of cancer stem/progenitor cells via binding to transcriptional factors." (PMID 36750914, 2023). "The overexpression of SIX1 increases phenotypic CSCs in some cancers, such as breast, esophageal, colorectal, and pancreatic cancers." (PMID 36750914, 2023). "SIX1 contributes to the development of these cancers through mechanisms such as controlling cell cycle progression and promoting metastasis." (PMID 38031089, 2023). "First, the expression of SIX1 in cancers and matched adjacent normal tissues were compared using the TIMER database." (PMID 35069900, 2022). "SIX1 is considered to be a cancer fetoprotein, and its inappropriate re-expression can lead to genome instability, malignant transformation, and metastasis." (PMID 35287543, 2022). "In this study, we investigated the role of cancer-associated fibroblasts (CAFs)-derived exosomal TUG1, SIX1 and miR-524-5p in the migration, invasion, and glycolysis in HCC cells." (PMID 35193488, 2022). "SIX1 has been shown to increase cancer cell proliferation and glycolysis by modulating PKM2 expression." (PMID 36276846, 2022). "Sine oculis-related homeobox 1 homolog (SIX1) is a transcription factor that regulates the development of many tissues and becomes reactivated or overexpressed in multiple types of human cancer." (PMID 35205261, 2022). "The transcriptional regulator Sox2 has been shown to be directly regulated in developmental and cancer contexts by Six1, Six2, Six3, and Six6 to further promote stem/progenitor cell phenotypes." (PMID 34490256, 2021). "In this study, we found that SIX1 was upregulated in various cancer cells and that SIX1 levels were negatively correlated with poor survival rates and immune cell infiltration in SARC." (PMID 34782761, 2021).
cancer (continued). "Sine Oculis Homeobox Homolog 1 (SIX1) is reported to promote cancer initiation and progression in many preclinical models and is demonstrated in human cancer tissues." (PMID 34745930, 2021). "The so subfamily (SIX1 and SIX2), particularly SIX1, have been frequently implicated in the promotion, invasion, and survival of a variety of cancers." (PMID 34490256, 2021). "Recent data suggest that several miRNAs including miR-362, miR-186-5p, and miR-188 target the 3ʹ untranslated regions (3ʹ UTRs) of the SIX1 mRNA to induce its degradation and inhibit its translation in several cancers." (PMID 34711117, 2021). "In the course of investigating the molecular mechanisms responsible for regulating the TME through aberrant gene expression in cancer cells, we found that SIX1 was highly expressed in the cancerous tissues of most tumors." (PMID 34782761, 2021). "Together, the data demonstrate that Six1 deletion in cancer cells enhances antitumor immune responses and especially stimulates cellular immune responses." (PMID 34782761, 2021). "The SIX family includes six members (SIX1–SIX6), of which the role of SIX1 in the occurrence and development of cancer has been widely investigated." (PMID 33481352, 2021). "SIX1 direct interaction with its co-activator EYA2 gives rise to a transcriptional unit that regulates multiple cancer hallmarks, including cell proliferation, invasion, and resistance to apoptosis." (PMID 34771571, 2021). "Increased expression of either SIX1 or SIX2 in several cancer types reduced the level of CDH1 through either activating known repressors of CDH1, such as Zeb proteins, or by CDH1 promoter methylation." (PMID 34490256, 2021). "The miR-548a-3p/SIX1 axis regulates aerobic glycolysis by alteration expression of glycolysis genes in cancer cells." (PMID 34671213, 2021). "In most adult tissue, SIX1 is little expressed; however, in some cancer tissues, the re-expression of SIX1 promoted cellular proliferation, migration and stem cell-like features by regulating cyclins and matrix metalloproteinase 9 (MMP9)." (PMID 34513929, 2021). "More works still need to improve the understandings of SIX1 expression and prognosis in different cancer types." (PMID 34745930, 2021). "SIX1 expressing is emerging as an important predictor of poor prognosis and more aggressive forms of cancer." (PMID 34564169, 2021). "Fused in sarcoma (FUS, a coactivator of NF-κB subunit RELA) was also regulated by SIX1 in cancer cells." (PMID 34513929, 2021). "SIX1 expression indicated its potential to serve as a cancer biomarker and deliver prognostic information in various cancer patients." (PMID 34745930, 2021). "In the primary and established NSCLC cells, forced overexpression of miR-7160 downregulated SIX1 and inhibited cancer cell growth, proliferation, migration and invasion." (PMID 33686961, 2021). "SIX1 is reported to be a key transcription factor in the regulation of the Warburg effect 14 and promotes the progression of various cancers." (PMID 32863962, 2020). "In accordance with this, we searched online databases and observed that SIX1 was frequently highly expressed in many cancers, including BC, and correlated with poor survival and high risk." (PMID 33293473, 2020). "EYA2 level was lower in cancer samples than normal breast samples while SIX1 level was higher in cancer samples than normal breast samples." (PMID 32550045, 2020). "Sine oculis homeobox 1 (SIX1), a key transcription factor for regulating aerobic glycolysis, participates in the occurrence of various cancer types." (PMID 32258386, 2020). "EMT transcription factors Twist1, Snail1 and Six1 would influence carcinoma cells by inducing EMT characteristics and aggressive properties." (PMID 31931858, 2020).
cancer (continued). "SIX1 is re-expressed in many cancers including breast, ovarian, colorectal, and hepatocellular carcinoma." (PMID 30962263, 2019). "In comparison with normal tissue, high expressions of SIX1 and EYA1 were associated with a malignant tumor." (PMID 31921695, 2019). "Comparing with pan-cancer driver genes, our study found that SIX1 was up-regulated, while TAL1 and ID4 were down-regulated in NSCLC." (PMID 31681566, 2019). "Ectopic expression of SIX1 ubiquitously exists in numerous types of cancer and plays important roles in both tumor initiation and progression." (PMID 31438963, 2019). "For example, microRNA-185 translationally represses SIX1 and thereby sensitizes SIX1-overexpressing cancer cells to TRAIL-induced apoptosis." (PMID 31921695, 2019). "Of note, studies on SIX1 in cancer so far have focused mostly on carcinomas, and thus the knowledge about the role of Six1 in tumors of non-epithelial origin is much more limited." (PMID 30723235, 2019). "To investigate the expression status of TFAP2A and SIX1 proteins in benign and malignant lung tissue, we performed IHC staining of 7 lung tumor samples and 7 adjacent non-cancer tissue samples." (PMID 30177858, 2018). "Among the top 50 targets predicted by miRanda, SIX1, a transcription factor reported to be involved in the proliferation and metastasis of several cancers, stood out among the numerous candidates." (PMID 29435409, 2018). "In accordance with the two previous studies, we observed an overexpression of Six1 in cancer cells compared to healthy tissue." (PMID 28388884, 2017). "Together these results demonstrated that Six1 is able to induce mitochondrial fission and maintain mitochondrial membrane potential, which reduced sensitivity of cancer cells to mitochondrial apoptosis." (PMID 29113360, 2017). "A positive nuclear expression of Six1 was observed in 40.8% (± 4.2) of cancer cells (0 = 81 cases; 1 = 31 cases; 2 = 17 cases, 3 = 4 cases, 4 = 4 cases)." (PMID 28388884, 2017). "For instance, miRNA-185 directly reduces SIX1 abundance and thereby sensitizes SIX1-overexpressing cancer cells to TRAIL-induced apoptosis." (PMID 27203207, 2016). "SIX1 combined with specific transcription factors increases a particular subpopulation of cancer stem/progenitor cells." (PMID 27203207, 2016). "Silencing SIX1 expression using short hairpin RNA (shRNA) or miRNA is now viewed as a potential cancer treatment strategy." (PMID 27203207, 2016). "The secretion of an oncogenic molecule such as SIX1 highlights the role of exosomes in cancer progression and elucidates their utility as a reservoir of disease biomarkers." (PMID 25944692, 2015). "Forementioned studies suggested that Six1 enhances cancer cell proliferation and shortens survival and its overexpression in immortalized mammary epithelial cells induces EMT, leading to highly aggressive and invasive tumors when transplanted into nude mice." (PMID 26161040, 2015). "Sineoculis homeobox homolog 1 (Six1), normally a developmentally restricted transcriptional regulator, is frequently dysregulated in mutiple cancers." (PMID 26161040, 2015). "It has been reported that Six1 is a cell cycle regulator and affects the cell cycle progression both in normal development and in cancer." (PMID 23527134, 2013). "Six1 is one of the transcription factors that act as master regulators of development and are frequently dysregulated in cancers." (PMID 23527134, 2013). "Of the miRNAs down-regulated in the metastatic xenografts, miR-185 has been shown to suppress growth and progression of certain human cancers (e.g., breast, ovary) by targeting the Six1 oncogene which regulates c-myc expression." (PMID 21980368, 2011). "Six1 is highly expressed in cancers derived from tissues in which it plays a fundamental role during embryogenesis, and recent work demonstrates that overexpression of Six1 leads to an expansion of mammary stem/progenitor cells." (PMID 20074369, 2010).